CFLAR (CASP8 and FADD like apoptosis regulator)
Diseases named in the same sentence as CFLAR in open-access papers (continued):
Sharing a sentence is not in itself a finding about the gene and the disease.
asthma (1 paper, 2018). "Furthermore, one of the limitations of the current study is that we cannot exclude that asthma status may have an influence on gene expression of CFLAR and CAP1." (PMID 30127367, 2018).
hepatitis C infection (1 paper, 2008). "Recent studies of hepatitis C infection directly implicate the sustained upregulation of the cFLAR gene product in preventing TNF-α-mediated apoptosis and contributing to disease initiation by the virus core protein." (PMID 19014542, 2008).
infarction (1 paper, 2023). A localised pathological necrosis of tissue resulting from obstruction of the blood supply usually by a thrombus, an embolus, or vascular torsion. "The expression CASP8 and FADD-like apoptosis regulator (cFlip), also known as Cflar, has been shown to be diminished in failing human and murine post-infarction hearts." (PMID 37426668, 2023).
influenza (1 paper, 2021). An acute viral infection of the respiratory tract, occurring in isolated cases, in epidemics, or in pandemics; it is caused by serologically different strains of viruses (influenzaviruses) designated A, B, and C, has a 3-day incubation period, and usually lasts for 3 to 10 days. "When evaluating the effects of both age and sex on gene expression in response to influenza stimulation, only CFLAR expression was statistically significant for age (p = 0.006), but not with sex (p = 0.057)." (PMID 35822051, 2021). "Notably, CFLAR expression was significantly higher among females (p = 2.42 × 10−5) following influenza stimulation." (PMID 35822051, 2021). "Interestingly, CFLAR expression was significantly higher among females (p = 2.42 × 10−5) following influenza stimulation and this gene may play an important role in the development of higher HAI antibody titers among older females." (PMID 35822051, 2021). "Our results also suggest that sex-based and age-based differences in CFLAR expression may play a role in influenza vaccine response, and replication of this finding with further studies are warranted in order to understand the complex influence of biological sex and age on the immune response." (PMID 35822051, 2021).
laryngeal carcinoma (1 paper, 2021). Carcinoma that arises from the laryngeal epithelium. "This suggests that EGFR and INHBA can serve as prognostic hub genes for laryngeal cancer collectively with pRS genes (CFLAR, DAPK2, TSC2, CAPN10, MBTPS2, PEX14, FADD and ST13)." (PMID 34093817, 2021).
latent infection (1 paper, 2014). "Moreover, we profiled the IRF4 transcriptome in the context of EBV latent infection, and confirmed several genes including IFI27, IFI44, GBP1, and ARHGAP18, as well as CFLAR as novel targets for IRF4." (PMID 25207815, 2014).
myeloid malignancy (1 paper, 2021). "Furthermore, since CUX1 haploinsufficiency predominates over complete CUX1 loss in myeloid malignancies, we wished to establish the relevance of findings by comparing the impact of CFLAR depletion in CUX1-haploinsufficient cells." (PMID 33931647, 2021). "Future studies will aim to examine the efficacy of combining PI3K-AKT pathway inhibition with CFLAR pathway-targeting agents in poor-prognosis -7/del(7q) myeloid malignancies." (PMID 33931647, 2021). "At present no pharmacological inhibitors of CFLAR are routinely available, but second mitochondria-derived activator of caspase (SMAC)-mimetics, such as birinapant, have attracted attention as therapies in cancer, including myeloid malignancies." (PMID 33931647, 2021).
retinoblastoma (1 paper, 2025). A malignant tumor that originates in the nuclear layer of the retina. "Based on data from the GEO database and GSEA analysis, we found that in retinoblastoma, caspase-3 is downregulated, while caspase-8 and c-FLIP (cFLAR) are upregulated." (PMID 40309730, 2025).
schizophrenia (1 paper, 2012). A major psychotic disorder characterized by abnormalities in the perception or expression of reality. "Our qRT-PCR investigation did not confirm or replicate the increased CFLAR expression observed in schizophrenia tissue by microarray." (PMID 22545112, 2012).
cancer (238 papers, 2007 to 2026). A tumor composed of atypical neoplastic, often pleomorphic cells that invade other tissues. "Mutation plays a devastating part in the development of several cancer and in the current study mutation in CFLAR andTRAF2, regulator of apoptotic pathway, disrupt the process of natural death in the cell." (PMID 34602774, 2021). "Our finding shows that CFLAR polymorphism plays important role in cancer cell death induced by triptolide." (PMID 26121980, 2015). "We found that cancer cells with lower levels of Lsd1 or higher levels of Oas1 or Oas3 were significantly more dependent on CFLAR." (PMID 38280853, 2024). "CFLAR is a known key regulator of the apoptotic signalling pathway and is abnormally expressed in a variety of cancers." (PMID 36186436, 2022). "The mutation in CFLAR and TRAF2 destructthe apoptotic process and the cell follows the proliferation step and resulted to numerous numbers of cancer cells in the body." (PMID 34602774, 2021). "In this study, PRMT5 protected NSCLC cells from caspase activation and apoptosis induced by anti-cancer drugs, and knocking down its expression led to CFLAR downregulation and activating chemotherapeutic-induced apoptosis." (PMID 34200178, 2021). "The current computational study was conducted to identify phytotherapeutic compound for inhibition of proliferation function in cancer cells through inhibiting the activity ofmutated CFLAR and TRAF2 function." (PMID 34602774, 2021). "Only a possible role of CFLAR isoforms in cancer can be inferred from this, which can also be concluded from a simple differential expression study." (PMID 25034693, 2014). "Nevertheless, the observed concordance between the DS-induced impact on both the CFLAR mRNA and cFLIP content suggests that an accumulation of the protein in both cancer cell lines results primarily from the stimulation of its synthesis rather than impaired degradation." (PMID 41148796, 2025). "CFLAR was found as an independent adverse prognostic biomarker in different cancer types." (PMID 39443755, 2024). "CFLAR is also considered a promising therapeutic target, and multiple approaches have been developed to interfere with CFLAR expression or function in human cancers." (PMID 36186436, 2022). "Taken together, these data suggest that cancer cells benefit from lower CFLAR expression and may achieve this outcome as a consequence of oncogenic signaling." (PMID 34545139, 2021). "These included genes involved in cell death and survival processes (BCLAF1, CFLAR, CASP1, and XIAP), genes associated with proliferation-driving transcription or cancer (KLF4, LEF1, SOX4, ID3), and genes associated with inflammation (CD28, CCR7, CX3CR1 and IFNG)." (PMID 28407008, 2017). "CFLAR has been described in multiple studies as being important in the development of cancer, and is therefore also being described as a target for therapy (reviewed by Fulda in 2013); it induces apoptosis, but is also a key role player in autophagy and necroptosis." (PMID 28407008, 2017). "Besides, CFLAR abnormal expression is related to the prognosis of human cancer." (PMID 34093817, 2021). "In addition, CFLAR is a common therapeutic target in various human cancers including OS." (PMID 34225733, 2021). "The expression of the CFLAR gene, which is an apoptosis regulator that may function as a crucial link between cell survival and cell death pathways in mammalian cells, is downregulated in both cancer cell lines (in comparison to HUVECs)." (PMID 24037645, 2013). "Of these DEGs, 6 (EGFR, GATA3, DIABLO, CFLAR, RIPK3, and MAPK8) were repressed, while (ZBP1, PLK1, SPATA2, BCL2, ALK, FASLG, TNFRSF21, and LEF1) were upregulated in cancer cases." (PMID 35610275, 2022).
cancer (continued). "Other proteins that are dysregulated in cancer are also affected by AIMs, including: JNK; JAK1 and STAT3; Her2 (ERBB2); death receptor 5 (TNFRSF10B); and cFLIP (CFLAR)." (PMID 25897966, 2015). "Regardless of the different phenotypes of the two cancer cell types, T3 decreased the levels of anti-apoptotic proteins (cIAP1, cIAP2, XIAP, cFLIP and Mcl-1) for a short period of exposure and altered the splicing of the anti-apoptotic MCL1L and CFLAR isoform in A2780 and HCT116 cells." (PMID 33064779, 2020).
tumor (194 papers, 2005 to 2026). "Besides, elevated expression of CFLAR is associated with tumor cells escaping from immune surveillance in vivo, correlates with a more aggressive tumor, and is also considered to be the main cause of immune escape." (PMID 39443755, 2024). "Genes including UACA and CFLAR exhibited elevated expression in epithelial cells, macrophages and endothelial cells, suggesting involvement in tumor-immune crosstalk." (PMID 41293156, 2025). "In turn, CD8 Tex cells in the LN-out highly expressed TGF-β1, IFN-γ, and ITGB1, which target FN1, EGFR, CTNNB1, COL1A1, and CFLAR in tumor cells, activating downstream pathways including ERK1 and ERK2 cascade." (PMID 38519500, 2024). "In particular, 12 genes, including AXL, CDH1, CFLAR, FKBP1A, NT5E, and VIM, were reported to be significantly associated with tumor metastasis (P<8E-04)." (PMID 23185353, 2012). "Notably, 8 autophagy-related genes (CAPN10, DAPK2, MBTPS2, ST13, CFLAR, FADD, PEX14 and TSC2) and 2 immune cells (Mast cells and Eosinophils) were revealed to be highly associated with tumor prognosis." (PMID 34093817, 2021). "Among these significant genes of IL-4 signaling are CFLAR, ALOX5, PMAIP1, EGR1, NCF2, SLC39A8, and PEG10 which have been reported to be associated with tumor progression or chemotherapy-drug resistance through effecting proliferation and apoptosis in previous studies." (PMID 33506057, 2021). "Top gene hits identified through both screens involved in for example TNFα signaling were CFLAR, MAPK1, RIPK1, TNFRSF1A, and ICAM1, highlighting their role in regulating tumor sensitivity to TNF-α-induced cell death." (PMID 37732732, 2023). "Several genes were found at lower expression levels in tumor cases, such as AXL, BAHC2, CFLAR, and DNMT1 while others were overexpressed such as BNIP3, DIABLO, FADD, and IDH1." (PMID 35911707, 2022). "Meanwhile, the relative expression of CFLAR and STC2 in tumor cells was significantly higher than that in normal cells (all P < 0.05)." (PMID 34225733, 2021). "Genes such as CFLAR, EP300, GBP2, HEYL, KLF7, NOTCH1 or POFUT showed a similar correlation with NUMB or NUMBL in the three tumor types considered." (PMID 29507685, 2018). "For example, TFs, such as ASH1L, CFLAR, HMGB3, ZNF160 and MATR3, displayed opposite behaviors on some cytokines; inflammatory factors; nuclear and tumor factors, such as IL-2, IL-6, NF-κB, and Irf3; immunogenic nucleic acids; papillomavirus E7/E6; caspase-3/caspase-8; Toll-like receptor; and so on." (PMID 28719625, 2017). "Studies have shown that cordycepin could inhibit TNF-signaling-induced MAPK activation, the expression of CFLAR, and regulate the CASP family and MMP family of proteins, thereby inhibiting tumor proliferation and metastasis while promoting apoptosis and autophagy in TNBC cells." (PMID 39000182, 2024).
infection (27 papers, 2008 to 2026). The state of being infected such as from the introduction of a foreign agent such as serum, vaccine, antigenic substance or organism. "Given these intimate associations of CFLAR with inflammation and cell death, we supposed that CFLAR might have a potential role in regulating damage caused by infection with V. harveyi." (PMID 39450165, 2024). "For other anti-apoptotic gene expressions, we found that MCL1 was upregulated, except in homeostatic Micro-0 and Micro-1, CFLIP (CFLAR) was upregulated in Micro-3 and Micro-11, and others remained unchanged or slightly downregulated in infection." (PMID 39283947, 2024). "We noted that cells remaining at 21 days following infection with CFLAR-targeting sgRNAs escaped CFLAR depletion, which likely accounts for their survival at this time." (PMID 33931647, 2021). "Interestingly, at 24 h after infection we observed enhanced systemic expression of antiapoptotic genes (e.g. CFLAR, MCL1)." (PMID 20184744, 2010). "In addition the Nf-κB inhibitor QNZ reduces cFLAR expression in agreement with its higher level in the toxigenic strain infection." (PMID 19014542, 2008). "However, in response to infection, male mice exhibited higher expression levels of CFLAR, and FKBP5 (KO, 1A3), AKT1, and CCL9 (1A3, 6A2), C1QC (6A2), LSP1 (1A3, 6A2, and 6A4), CKAP2, and KAT2B (KO), TACC2 (1A0), RCC2 (1A3, 6A2), PPARG (1A3, 6A4), and ERP44 (6A2) compared to females." (PMID 32670284, 2020). "We found collectively among SP-A variants several genes such as AKT1, BTK, CCL9, PPARG, and RELA to exhibit higher expression in females, whereas, CFLAR, C1QC, LSP1, CKAP2, KAT2B, TACC2, and RCC2 exhibited higher expression in males after infection." (PMID 32670284, 2020). "Furthermore, anti-apoptotic genes, GADD45B and CFLAR, and the IAP family members (BIRC2 and BCL2L1) were upregulated early or late after DTMUV infection." (PMID 32897243, 2020). "Interestingly, infection with the clinical isolate UT205 exclusively induced the expression of the P2RX7 gene, which with other genes such as CFLAR and BIRC3, showed enrichment in processes of cell death by necrosis and necroptosis." (PMID 32391286, 2020). "The female mice exhibited higher expression levels of AKT1, BTK, CCL9, and LSP1 (KO, 1A0), PPARG (KO, 1A0, and 6A2), CFLAR, and ERP44 (1A0, 6A4), CCL9 (KO, 1A0, and 6A4), RCC2, and RELA (KO), KAT2B (6A2) and FKBP5 (1A0, 6A2, and 6A4) compared to males in response to infection." (PMID 32670284, 2020). "Based on our findings, we observed significant downregulation of the apoptosis pathway CFLAR, as well as upregulation of CASP3/8, indicating that T lymphocytes enter the apoptosis pathway in the late stage of infection, while B cells may contribute to adaptive immunity." (PMID 38203332, 2023). "Venn diagram analysis showed that among the common DGEs in the 3 h and 12 h infection groups compared with the control group, 11 differential genes were enriched in the NF-κB signaling pathway, including CXCL8, IL-1β, CCL4, IκBα, TNF, NF-κB, CFLAR, PTGS2, TRAF1, PLAU, and IL-1β2." (PMID 35215890, 2022). "The time-course experiment revealed that upon adsorption and early during infection (4 h and 8 h), no significant modulation in the AS profiles of ABI1, CFLAR and IL34 could be detected." (PMID 35489070, 2022). "Therefore in the absence of cFLAR induction, and in conjunction with the observed TNF-α production, we hypothesize that infection in the absence of pXO1 probably induces apoptosis through a classical extrinsic TNF-α receptor-mediated caspase-8 pathway." (PMID 19014542, 2008).
inflammation (2 papers, 2020 to 2021). Aberrant reaction of the microcirculation characterized by movement of fluid and leukocytes from the blood into extravascular tissues. "A follow up study identified CFLAR, a gene encoding c-FLIP (cell death regulator), as a susceptibility gene for cigarette smoke-induced airway inflammation and confirmed that CLFAR expression is decreased in response to cigarette smoke extract (CSE)." (PMID 34685744, 2021).
metabolic disorders (2 papers, 2020). "CASP8 and FADD-like apoptosis regulator (CFLAR)/cFlip have been reported as an essential suppressor of steatohepatitis and its metabolic disorders." (PMID 33353156, 2020).
CFLAR also shares sentences with these, for which no sentence is quoted: prostate carcinoma (45 papers); glioma (21); colon carcinoma (16); non-small cell lung carcinoma (16); cervical carcinoma (12); ovarian carcinoma (12); acute myeloid leukemia (11); viral infection (10); bladder cancer (8); lung adenocarcinoma (8); COVID-19 (6); head and neck squamous cell carcinoma (6); osteosarcoma (6); pancreatic ductal adenocarcinoma (6); renal cell carcinoma (6); Burkitt lymphoma (5); endometrial carcinoma (5); neuroblastoma (5); T-Cell Lymphoma (5); triple-negative breast carcinoma (5); prostate tumor (4); acute lymphoblastic leukemia (3); B-cell chronic lymphocytic leukemia (3); cholangiocarcinoma (3); glaucoma (3); head and neck cancer (3); malignant glioma (3); myeloma (3); primary effusion lymphoma (3); sarcoma (3).
A further 120 diseases each share a sentence with CFLAR in 2 papers or fewer.